TNF (tumor necrosis factor)
Diseases named in the same sentence as TNF in open-access papers (continued):
Sharing a sentence is not in itself a finding about the gene and the disease.
mastitis (continued). "qRT-PCR and ELISA were performed to measure the levels of IL-6, TNF, and IL-1β in the breast tissue of mice with LPS-induced mastitis, with or without ammonia treatment." (PMID 40370468, 2025). "In cows with subclinical mastitis, dietary supplementation with inulin reduced the SCC in milk and decreased the concentrations of proinflammatory cytokines, including IL-6, IL-8, and TNF-α, while improving oxidative stress in the mammary glands." (PMID 41139776, 2025). "Additionally, a recent study found that levels of IL-6, IL-1β, TNF-α, and MPO were all increased in mice that developed mastitis due to S. aureus." (PMID 41148692, 2025). "Regarding the impact of pathogen type on the reproductive performance of cows, Gram-negative mastitis pathogens, particularly E. coli can induce a massive release of cytokines such as tumor necrosis factor-alpha (TNF-α), interleukin (IL)-1β, IL-8, and others." (PMID 41463693, 2025). "The results revealed that the binding energy between GYS components and relevant targets was less than -5 kcal/mol, which suggested that TNF and IL-6 might be the primary targets of GYS in mastitis treatment." (PMID 38630770, 2024). "Similarly, rosmarinic acid and nuciferine alleviate LPS-induced mastitis by inhibiting the TLR4/MyD88/NF-κB signaling pathway and production of TNF-α, IL-1β, and IL-6 in MMECs." (PMID 39199398, 2024). "Furthermore, in vivo tests indicated that intramammary infusion of L. casei 03 relieved pathological changes, reduced the secretion of IL1β, IL6 and TNFα and MPO activity in the mouse mastitis model." (PMID 38395896, 2024). "Furthermore, it has been documented that diosmetin relieved S. aureus-induced mastitis in mice by inhibiting the expression of MPO, TNF-α, IL-1β, and NF-κB." (PMID 39199398, 2024). "Therefore, although there is variation in the time since the onset of inflammation in the spontaneous mastitis cases in this study, the correlations among SCC, IL-6, and TNF-α in milk were confirmed because these dynamics are similar during inflammation." (PMID 39872610, 2024). "Moreover, using PPI network analysis, we determined that TNF, IL-6, IL-1β, CXCL8, and ICAM1 proteins were the main targets of GYS for mastitis treatment." (PMID 38630770, 2024). "Kaempferol suppressed phosphorylation of the NF-κB p65 subunit and the degradation of its inhibitor, IκBα, in the NF-κB signal pathway for the treatment of mastitis; this was accompanied by decreased myeloperoxidase (MPO) production and ANGPTL2 expression, as well as a reduction in TNF-α and IL-6." (PMID 38630770, 2024). "Likewise, dose-dependent decreases in several inflammatory markers during mastitis, including MPO activity, and TNF-α and IL-1β, were detected after HEX treatment compared with S. aureus treatment." (PMID 37948460, 2023). "Serum IL-6 levels in the PUE-fed control healthy cows were significantly lower than those in the mastitis group (p < 0.01), and the expression of TNF-α and IL-1β also decreased, but there was no statistical significance." (PMID 37175449, 2023). "LncRNAs such as LOC107133214, LOC104974443 and LOC101906793 can regulate the expression of inflammatory and cell death-related mRNAs such as IL-6, NFKB1 and TNFAIP3 and participate in the process of mastitis through NOD-like receptor, TNF, MAPK and other signaling pathways." (PMID 37845761, 2023). "IL-2, TNF-α, and IFN-γ have a vital role in mastitis prevention, according to bovine studies." (PMID 36960295, 2023). "Microbiota from cows with mastitis enhanced the expression of several inflammatory markers in murine mammary glands, including NF-κB, MAPK-ERK, MAPK-p38, MAPK-JNK, and STAT3, and the production of IL-6 and TNF-α." (PMID 36422325, 2022). "No significant change in gene expression of IL-2, IL-4, IL-6, IL-8, IL-10, IFN-γ, and TNF-α by real-time PCR in milk among animals without mastitis vs. animals with mastitis was observed." (PMID 35335696, 2022).
mastitis (continued). "The cytokine arrangement (IL-1, 2, 4, 6, and 8, TNF-α and IFN-γ) measured in the milk of the cows of this study could represent the most common mediators in bovine mastitis studies." (PMID 34887474, 2021). "Our research results showed that PE could significantly inhibit the increase in the levels of inflammatory mediators such as TNF-α, IL-6, IL-1β, MPO and iNOS during mastitis." (PMID 34383710, 2021). "CmCGG DMEGs like IL6R, TNF, BTK, IL1R2, and TNFSF8 enriched in several immune-related GO terms and pathways indicated their important roles in host immune response and their potential as candidate genes for S. aureus mastitis." (PMID 33193625, 2020). "In addition, based on published literature, we concluded that TLR4, IL-1β, IL-6, TNF-α and MYD88 are key players in NF-κB signaling and also have an essential role in mastitis development." (PMID 32927884, 2020). "Enrichment of “TNF signaling pathway,” “NF-kappa B signaling pathway,” “Toll-like receptor signaling pathway,” and “MAPK signaling pathway” in the purple module revealed the potential functions of its members in mastitis pathogenesis." (PMID 32754201, 2020). "IL-1 likewise TNF-α is an inflammatory cytokine, but IL-1 involvement in mastitis pathogenesis is not decisive and its significance is influenced by the type of infectious agent as discussed by Alluwaimi and Shuster and Kehrli." (PMID 32256195, 2020). "The potential signaling pathways that key CMM combinations may involve in during mastitis treatment were NF-κB signaling pathway, immune system, PI3K/Akt signaling pathway, and TNF signaling pathway." (PMID 30911319, 2019). "The present study demonstrates that berberine hydrochloride exerts anti-inflammatory effects by inhibiting inflammatory cell infiltration, the production of TNF-α, IL-1β, and IL-6, and the activation of the TLR4/NF-κB signaling pathway in a mouse model of mastitis." (PMID 29849710, 2018). "We detected significantly elevated levels of TNF-α and IL6 protein secreted in medium by INFs compared with that secreted by NFs, suggesting that mammary stromal fibroblasts contribute to the inflammatory response during mastitis." (PMID 27272504, 2016). "Also, in an LPS-induced mouse mastitis model and in LPS-treated mouse mammary epithelial cells, GLY treatment significantly reduced MPO activity and protein expression of TNF-α, IL-1β, and IL-6." (PMID 27792814, 2016). "IL1-beta is found in greater concentration in milk of E. coli mastitis than in milk of S. aureus mastitis, and TNF-alpha is found in bovine milk in case of E. coli but not S. aureus mastitis." (PMID 25948480, 2015). "In particular IL-1β is found in greater concentration in milk of E. coli mastitis than in milk of S. aureus mastitis, and TNF-α is found in bovine milk in case of E. coli but not S. aureus mastitis." (PMID 23758654, 2013). "Similarly, another study reported that Brazilin (isolated from the traditional herbal medicine Caesalpinia sappan L.)suppressed TLR2, TNF-α, IL-1β, and IL-6 levels by inhibiting the TLR2/NF-κB/MAPK signaling pathways in mammary gland tissues, thus preventing S. aureus-induced mastitis." (PMID 39199398, 2024). "Moreover, we found that the SRMT group had several increases in mastitis parameters, including MPO activity, TNF-α, and IL-1β levels, compared with the control and HRMT groups; however, zanamivir treatment alleviated these increases compared with those of the SRMT group." (PMID 37069691, 2023). "Moreover, in the early or late stages of breast infection with pathogens, MECs and their recruited immune cells can secrete specific innate immunosoluble cytokines or chemokines (CCL2, CCL 5, CCL 20, CXCL10, TNF-α, MyD88, etc.)." (PMID 36672605, 2022).
mastitis (continued). "Moreover, genome-wide DNA methylation alteration in the format of CmCGG was significantly related to the immune response to S. aureus-induced mastitis, and several genes including IL-6R, TNF, BTK, IL-1R2, and TNFSF8 were identified as potential epigenetic markers of S. aureus mastitis." (PMID 33708235, 2020). "In addition, TLR4, IL-1β, IL-6, TNF-α, MYD88 and NF-κB might be a useful addition as markers in mastitis control strategies." (PMID 32927884, 2020). "This study found that farrerol could improve pathological injury of mammary glands, attenuate the activity of MPO, inhibit the production of pro-inflammatory mediators (TNF-α, IL-6, IL-1β, iNOS and COX-2) and the phosphorylation of AKT, NF-κB p65, p38 and ERK1/2 in LPS-induced mouse mastitis." (PMID 29904013, 2018). "A failure of efficient killing of some mastitis pathogens (e.g., S. uberis) after engulfing and even increased intracellular multiplication of S. uberis as well as lesser stimulatory responses by IFN-γ to release TNF-α and bactericidal products compared to blood monocytes have been also reported." (PMID 26464939, 2014). "Experimentally induced E. coli mastitis is characterized by high concentrations of chemokines and cytokines in milk, whereas these inflammatory mediators, and in particular the chemokine CXCL8 and the cytokine TNF-α, are undetectable or in low concentrations in case of S. aureus mastitis." (PMID 23758654, 2013). "For this purpose, the expression of the interleukin 2 (IL-2), IL-4, IL-6, IL-8, IL-10, interferon gamma (IFN-γ) and tumor necrosis factor alpha (TNF-α) genes was investigated in Black and White (BW) Holstein and Gyr cows with and without clinical signs of mastitis." (PMID 21637453, 2009). "It should be emphasized that the IL-4, IL-6, IL-8 and TNF-α genes were not differentially expressed in any of the conditions studied (p > 0.05), demonstrating that these genes are not good markers or indicators of mastitis under the analyzed conditions." (PMID 21637453, 2009). "The cytokines in serum such as interleukin-4 (IL-4), IL-6, IL-17, tumor necrosis factor-α (TNF-α) and interferon-γ (IFN-γ) also act as indirect indexes in inflammatory conditions, which suggests that beside SCC and SCS, serum cytokines could be considered as crucial indicators for bovine mastitis." (PMID 28101335, 2017). "The P2X7R significantly decreased after LPS induction in bMECs, Overall, TNFα and IL1β are likely to be mainly produced by the resident or recruited leucocytes rather than by MEC in mammary during mastitis." (PMID 35812870, 2022). "In the current investigation, qRT-PCR was used to measure the levels of antioxidant (CAT, GPX1, Keap1, OXSR1, ATOX1, GST, and Nrf2) and immune (IFN-γ, IL-4, TNF-α, MYD88, CCL5, TLR4, TLR9, LTF, and PRLR) genes in Barki ewes that were resistant and non-resistant to mastitis." (PMID 40542007, 2025). "Pretreatment with DCA intraperitoneally, but not CA, alleviated S. aureus-induced mastitis, as evidenced by DCA improving mammary injury, mammary S. aureus burden, proinflammatory markers including TNF-α, IL-1β and IL-6 and MPO activity compared with that of the S. aureus group." (PMID 36755021, 2023).
dengue (211 papers, 2008 to 2026). "Consistent with our results, in vitro co-infection of human PBMC with DENV and CHIKV significantly suppressed CHIKV replication and increased secretion of IL-6 and TNF-α, two proinflammatory cytokines highly associated with dengue pathogenesis." (PMID 40920827, 2025). "Even host genetic factors such as genetic variants in FcγRIIa, DC-SIGN, MHC genes, MBL2, CCL-2, TNF-alpha, etc., contribute towards the progression to severe dengue." (PMID 40880375, 2025). "Tumor necrosis factor-α (TNF-α) is one of the cytokines involved in vascular activation that has also been implicated in the immunopathology of vascular leakage in severe dengue." (PMID 38793609, 2024). "Direct binding to TLR-4 increases expression of various cytokines and vasoactive amines e.g. interleukin 6 or TNF- alpha which increase the risk of vascular disorders leading to severe dengue." (PMID 40093849, 2024). "The substantial number of studies focused on TNF-alpha gene polymorphisms in this review highlights the importance of this cytokine in severe dengue pathogeneses." (PMID 38055376, 2023). "Larger, multi-center studies with standardized methodologies and thorough genetic analysis are needed to clarify the association between TNF-alpha gene polymorphisms and severe dengue risks." (PMID 38055376, 2023). "Inflammation is a characteristic of murine infection with DENV, and high levels of circulating TNF-α and IL-1β in patients are associated with severe dengue." (PMID 37515098, 2023). "IgG-mediated ADE significantly increases production of pro-inflammatory cytokines including type I interferon, IL-6, MIP-1α, and TNF, which are associated with dengue symptoms and development of pathogenesis." (PMID 37639455, 2023). "Eventually elevated levels of inflammatory cytokines (especially TNF-α and IL-6) potentiate cascade of events that culminate in vascular permeability and haemorrhage, which is the leading cause of severe dengue illness." (PMID 36658277, 2023). "Eight of the studies in our systematic review specifically investigated the association between TNF-alpha gene polymorphisms and severe dengue in Latin America." (PMID 38055376, 2023). "The elevation of pro-inflammatory cytokines especially TNF-⍺ and IL-6 are a major factor to cause the severe dengue disease, as these cytokines attract and facilitate monocytes infiltration at the site of DENV deposition or infection." (PMID 36658277, 2023). "Future research should also explore the role of interactions between TNF-alpha polymorphisms and other immune system genes in the pathogenesis of dengue, to further elucidate the genetic factors influencing individuals’ susceptibility to severe dengue." (PMID 38055376, 2023). "KEGG signalling pathway analysis revealed that MAPK, TNF, FoxO, and ferroptosis are thought to be closely associated with the pathogenesis of dengue." (PMID 36091000, 2022). "Multiple studies have shown that high levels of IFN-γ and TNF-α are associated with Dengue severity." (PMID 35864519, 2022). "Cytokines as IL-1β, IFN-γ, and TNF-α are elevated in severe dengue patients and associate with the degree of thrombocytopenia, hemodynamic instability, and disease severity." (PMID 36569864, 2022). "Among these immune parameters, TNF-α was shown to be positively linked to dengue-associated hematological changes in thrombocytopenia and vascular dysfunction." (PMID 34041302, 2021). "CRP/SAP as well as TNF-α/IL-1β were independently associated with both dengue severity and overall disease manifestation." (PMID 33436908, 2021). "Of note, significantly higher proportions of TNF-α secreting granulocytes and monocyte subsets at admission were associated with mild dengue and minimal symptoms." (PMID 34335578, 2021). "In DENV-2 genotype, T164S mutation in NS1 protein ascertains the fact that mutation in dengue protein can enhance clinical severity, as well as increased Th1 response—IL-6, IFNγ, and TNFα—in in vivo and in vitro experimental model." (PMID 34447698, 2021).
dengue (continued). "For example, increased TNF-α level was associated with increased severity of dengue and thrombocytopenia." (PMID 32751561, 2020). "Several cytokines found in the circulation of severe dengue patients have been shown to be associated with plasma leakage, including TNFα and IL-8." (PMID 33216752, 2020). "IFN-γ-mediated immune responses are described as crucial for viral clearance in DENV-infected mice, both for the early and late stages of infection, while TNF and IL-6 are associated with severe dengue in mice and humans." (PMID 35047876, 2020). "In fact, TNFα is associated with dengue severity in patients inducing vascular permeability, as well as metalloproteinases that would act on endothelial cells." (PMID 30986974, 2019). "Consistent with dengue-associated cytokine profiles reported in humans, increased IL-6, IL-8, TNF-α and MCP-1 levels were detected in most groups after challenge." (PMID 31009499, 2019). "Our finding is consistent with other studies in association of IL-6, IL-8, IL-15, MCP-1, and TNF-α in dengue fever." (PMID 30626045, 2019). "Gastrointestinal bleeding is a hallmark of severe dengue disease and previous reports implicate inflammatory cytokines such as TNF-α as a major player in this event." (PMID 31632411, 2019). "Studies have shown that increased levels of TNFα are associated with increased vascular permeability in patients with Dengue." (PMID 30112159, 2018). "A published meta-analysis has documented that TNF- α -308 G>G genotype and allele G confer susceptibility to symptomatic dengue, while TNF- α -308 G>A genotype and allele A confer protection." (PMID 30300401, 2018). "Even the immune system genes associated with dengue illness, such as TNF-α, IL-10, TGF-β1, FcγRIIa and CD209, can also be related with the RXRA gene in several pathways, as their expression is controlled by dimers formed by RXRA and other nuclear factors." (PMID 28241052, 2017). "Apart from the existing drawbacks regarding animal models to reproducing dengue, reports showed that the inhibition of TNF-α by administrating specific antibodies was associated with reduced severity." (PMID 28006034, 2016). "Evaluation of genetic predisposition to severe dengue also yields conflicting conclusions with regards to TNFα polymorphisms." (PMID 27007501, 2016). "All of findings suggest a pathogenic role for TNF-α in dengue-associated hemorrhagic disorders; however, regulation of TNF-α production still needs to be investigated." (PMID 27561946, 2016). "Single-nucleotide polymorphisms of TNF-α at the TNF-308A allele were also identified as a risk factor for hemorrhagic manifestations in severe dengue patients." (PMID 27561946, 2016). "High producing TNFα allele 308A has been determined to be a risk factor for bleeding manifestations during severe dengue." (PMID 27007501, 2016). "Similar to monocytes, IL-6 and TNF-α are implicated in both the protection and immunopathogenesis of dengue virus infection." (PMID 26226614, 2015). "The involvement of TNF-α in dengue-associated vascular leakage has been shown in vitro but has yet to be directly demonstrated in an in vivo model of severe dengue." (PMID 24699622, 2014). "Studies have reported a significantly higher level of TNFα in dengue-infected patients compared to healthy controls, and the elevated TNFα is associated with disease severity." (PMID 24727912, 2014). "Using a mouse model, a direct relationship between TNF-α and dengue hemorrhage was identified, because TNF-α deficiency greatly diminished hemorrhage development." (PMID 25580138, 2014). "TNF-α is known to play a pivotal role in the vascular leakage syndrome, a hallmark of dengue hemorrhagic fever." (PMID 25340500, 2014). "Using an 8-color flow cytometry panel, we then measured the number of CD3+ CD4+ or CD3+ CD8+ T cells producing cytokines that have been implicated in natural dengue disease: IFNγ, TNFα, IL2, and IL10." (PMID 22816004, 2012).